LYPLAL1 (lysophospholipase like 1)
Description:
Palmitoyl thioesterase that catalyzes depalmitoylation of CGAS and KCNMA1. Acts as a regulator of innate immunity by mediating depalmitoylation of CGAS, thereby preventing CGAS homodimerization and cyclic GMP-AMP synthase activity. Does not exhibit phospholipase nor triacylglycerol lipase activity, able to hydrolyze only short chain substrates due to its shallow active site.
Synonyms: Q96AV0
Tractability: Small molecule: a structure with a bound ligand is known. PROTAC: ubiquitination databases record sites on it; its protein half-life has been measured.
Target class: Enzyme; Hydrolase
Gene: Protein-coding gene on chromosome 1 (219,173,853 to 219,220,700, forward strand). Ensembl gene ENSG00000143353.
Subcellular location: Cytoplasm, cytosol (Isoform 1); Cytoplasm, cytosol (Isoform 2)
Subcellular location (Human Protein Atlas): Cytosol
Gene Ontology:
Molecular function: hydrolase activity, acting on ester bonds; lipase activity; palmitoyl-(protein) hydrolase activity; protein binding; phosphatidylcholine lysophospholipase activity; hydrolase activity
Biological process: negative regulation of cGAS/STING signaling pathway; negative regulation of Golgi to plasma membrane protein transport; macromolecule depalmitoylation
Cellular component: cytosol; mitochondrion; cytoplasm
Genetic constraint (gnomAD): Loss-of-function variants: 15 observed, 12.21 expected, observed/expected ratio (o/e) 1.23, 90% interval 0.82 to 1.8. The upper end of that interval is the gene's LOEUF score, 1.8, which puts it in group 6 of 6, group 1 being the genes least tolerant of losing a copy. Missense variants: 274 observed, 208.46 expected, observed/expected ratio (o/e) 1.31, 90% interval 1.19 to 1.45. Synonymous variants: 95 observed, 79.02 expected, observed/expected ratio (o/e) 1.2, 90% interval 1.02 to 1.43.
Homologues: Orthologues: chimpanzee LYPLAL1 (99% identical), macaque LYPLAL1 (95% identical), dog LYPLAL1 (89% identical), rabbit LYPLAL1 (87% identical), pig LYPLAL1 (85% identical), guinea pig LYPLAL1 (84% identical), mouse Lyplal1 (76% identical), tropical clawed frog lyplal1 (62% identical), rat Lyplal1 (58% identical), zebrafish lyplal1 (57% identical), Drosophila melanogaster CG6567 (43% identical), Caenorhabditis elegans ath-1 (26% identical). Paralogues in human: LYPLA1 (32% identical), LYPLA2 (31% identical).
Diseases named in the same sentence as LYPLAL1 in open-access papers:
LYPLAL1 is named in the same sentence as 20 diseases in open-access papers, as found by Europe PMC text mining. Sharing a sentence is not in itself a finding about the gene and the disease. The quoted sentences say what the papers report.
Obesity (14 papers, 2009 to 2025). Accumulation of substantial excess body fat. "In Benjamin AM’s study, they found that there was a sex-influenced association between genetic variation at the LYPLAL1 locus and obesity-related traits." (PMID 35432207, 2022). "A recent genome-wide association study modeling the effect of genotype-by-sex interaction on obesity phenotypes demonstrated sex-influenced associations between genetic variation at the LYPLAL1 locus and obesity-related traits." (PMID 24879436, 2014). "The variants near TFAP2B appear to influence central adiposity through an effect on overall obesity/fat-mass, whereas LYPLAL1 displays a strong female-only association with fat distribution." (PMID 19557161, 2009). "On the basis of eQTLs and limited transcription data, in two previous studies, it was proposed that a few obesity GWAS-derived SNPs that were ascribed to LYPLAL1 may actually be associated with RP11-391O17.1." (PMID 35163195, 2022). "Importantly, these previously identified obesity GWAS SNPs that other investigators associated with LYPLAL1 exhibit moderate LD (r2 = 0.35 to 0.68, EUR) with Tier-1 SNPs in the promoter region of RP11-392O17.1." (PMID 35163195, 2022). "A study in mouse GWAS has identified 11 genome-wide significant loci to be associated with obesity traits, and a PL-metabolizing enzyme lysophospholipase-like 1 (LYPLAL1) was among these loci identified in the epididymal adipose tissues of diet-induced obese mice." (PMID 32957701, 2020). "Among the genes in this locus, LYPLAL1, which encodes for lysophospholypase-like 1, appears to be the most likely effector gene, as it has been found to be downregulated in mouse models of diet-induced obesity and upregulated during adipogenesis." (PMID 29358691, 2018). "Thus, this underlying insulin resistant phenotype might add to explain the associations found between the LYPLAL1 variant and obesity." (PMID 21674055, 2011). "We exemplify this by identifying a putative long range cis regulatory mechanism at the LYPLAL1/TGFB2 obesity locus." (PMID 35746833, 2022). "Nonetheless, in 13 obesity-related GWAS, many candidate risk SNPs upstream of RP11-392O17.1 were assigned to LYPLAL1 rather than to the much closer RP11-392O17.1." (PMID 35163195, 2022). "However, analyses were made without adjusting for multiple testing, and further studies are needed to confirm the putative role of LYPLAL1, NRXN3, MSRA, and TFAP2B in the pathophysiology of obesity." (PMID 21674055, 2011). "However, analyses were made without adjusting for multiple testing, and further studies are needed to elucidate the involvement of LYPLAL1, NRXN3, MSRA, and TFAP2B in the pathophysiology of obesity." (PMID 21674055, 2011). "However, LYPLAL1 displays no preferential expression in any obesity-relevant tissue, unlike RP11-392O17.1." (PMID 35163195, 2022).
central obesity (4 papers, 2010 to 2018). "We demonstrate that several of the central obesity-associated variants in LYPLAL1, NRXN3, MSRA, and TFAP2B associate with metabolic and anthropometric traits in Danish adults." (PMID 21674055, 2011). "As a major finding the G-allele (risk-allele) of rs2605100 in LYPLAL1 associated with elevated concentrations of fasting serum triglycerides and fasting serum insulin and with estimates of central obesity." (PMID 21674055, 2011). "The aim of the present study was to investigate central obesity-associated variants in LYPLAL1, NRXN3, MSRA, and TFAP2B for associations with quantitative metabolic traits in a population-based sample of 6,038 adult Danes (The Inter99 study sample)." (PMID 21674055, 2011). "In this study we found several associations with quantitative metabolic and anthropometric traits for the central obesity-associated variants in LYPLAL1, NRXN3, MSRA, and TFAP2B." (PMID 21674055, 2011). "In conclusion, we found that several of the central obesity-associated variants in LYPLAL1, NRXN3, MSRA, and TFAP2B associated with metabolic and anthropometric traits among adult Danes." (PMID 21674055, 2011). "Genome-wide association studies (GWAS) have detected association between variants in or near the Lysophospholipase-like 1 (LYPLAL1) locus and metabolic traits, including central obesity, fatty liver and waist-to-hip ratio." (PMID 29084768, 2017). "Lastly, recent studies have indicated that there may be an association between diet and body composition and have highlighted specific interactions between central obesity associated genetic loci and healthy diet scores (for eg. at GRB4 and LYPLAL1 loci)." (PMID 29477148, 2018).
Hepatic steatosis (4 papers, 2017 to 2020). Steatosis is a term used to denote lipid accumulation within hepatocytes. "Upregulation of ADRP levels, PNPLA3/ADI polymorphisms, liver lipase (LIPC/HTGL) and lysophospholipase-like protein 1 (LYPLAL1) gene mutations, and DGAT2 enzymes involved in TG synthesis are also associated with the risk of liver steatosis." (PMID 33147895, 2020).
type 2 diabetes (4 papers, 2013 to 2024). "Lyplal1 has been associated with type 2 diabetes including through use of first-phase insulin secretion as a marker to identify candidate interacting SNPs." (PMID 33784857, 2021). "Other genes that were assigned to lead SNPs are involved in regulating satiety and energy homeostasis (MC4R;), adiposity (LYPLAL1;), and metabolic diseases such as type 2 diabetes (KLF14;)." (PMID 38664839, 2024).
steatosis (3 papers, 2020 to 2025). Increased lipid within the cytoplasm of cells. "The specificity of variant-metabolite associations were compared to metabolite associations with ultrasound-defined steatosis, gene variants linked to liver fat (in GCKR, PPP1R3B and LYPLAL1) and gene variants linked to cirrhosis (in HFE and SERPINA1)." (PMID 32720691, 2020). "Several studies do not provide evidence supporting the association between LYPLAL1 rs12137855 and NAFLD steatosis." (PMID 37632067, 2023).
lipodystrophy (2 papers, 2018 to 2023). A congenital or acquired disorder characterized by abnormal loss or redistribution of the adipose tissue in the body. "The weighted loci in this cluster (N = 37 loci) are lipodystrophy and adiposity-related variants (PPARG, IRS1, LYPLAL1, and DNAH10)." (PMID 37790568, 2023).
diabetes (1 paper, 2024). "Consequently, due to its benefits, we may infer that lncRNA LYPLAL1 expression is an independent predictor of MVC that could represent a safe, viable future marker for diabetes and associated macrovascular complications." (PMID 39406930, 2024).
dyslipidemia (1 paper, 2023). "This study uses OS and genes (LYPLAL1, APOC3 and SOD2) as research variables, and explores their association with dyslipidemia in coal workers from the perspective of the interaction between environment and genetics." (PMID 36759651, 2023). "Therefore, in this study, we selected rs12137855 in the LYPLAL1 gene, rs2854116 in the APOC3 gene and rs4880 in the SOD2 gene to investigate the association of three gene polymorphism, OS and their interaction with dyslipidemia." (PMID 36759651, 2023).
myopia (1 paper, 2012). "While the relationship between LYPLAL1 and myopia is unknown, elevated saturated-fat intake has been proposed to influence myopia development through the retinoid receptor pathway." (PMID 22685421, 2012). "In addition, variations in the expression of murine gene ZC3H11A and two neighboring genes SLC30A10 and LYPLAL1 in the retina and sclera in a myopic mouse model implicate the role of these genes in myopia onset." (PMID 22685421, 2012).
metabolic disease (2 papers, 2017 to 2024). A congenital disorder (due to inherited enzyme abnormality) or acquired (due to failure of a metabolically important organ) disorder resulting from an abnormal metabolic process. "Likewise, Lyplal1 expression was lower in kidney fat of Zucker diabetic fatty rats, compared with Zucker lean rats, yet LYPLAL1 expression is increased in WAT from obese patients and in the liver in mouse metabolic disease models." (PMID 29084768, 2017).
LYPLAL1 also shares sentences with these, for which no sentence is quoted: Insulin resistance (4 papers); cancer (1); cardiac hypertrophy (1); Cirrhosis (1); coronary artery disease (1); Liver Disease (1); non-alcoholic steatohepatitis (1); nonalcoholic fatty liver disease (1); prostate carcinoma (1); tumor (1).